ABRAXAS2 (abraxas 2, BRISC complex subunit)
Description:
Component of the BRISC complex, a multiprotein complex that specifically cleaves 'Lys-63'-linked polyubiquitin, leaving the last ubiquitin chain attached to its substrates. May act as a central scaffold protein that assembles the various components of the BRISC complex and retains them in the cytoplasm. Plays a role in regulating the onset of apoptosis via its role in modulating 'Lys-63'-linked ubiquitination of target proteins (By similarity). Required for normal mitotic spindle assembly and microtubule attachment to kinetochores via its role in deubiquitinating NUMA1. Plays a role in interferon signaling via its role in the deubiquitination of the interferon receptor IFNAR1; deubiquitination increases IFNAR1 activities by enhancing its stability and cell surface expression. Down-regulates the response to bacterial lipopolysaccharide (LPS) via its role in IFNAR1 deubiquitination.
Synonyms: ABRO1; FAM175B; KIAA0157; Em:AC068896.4
Tractability: Small molecule: a structure with a bound ligand is known. PROTAC: ubiquitination databases record sites on it.
Gene: Protein-coding gene on chromosome 10 (124,801,805 to 124,836,670, forward strand). Ensembl gene ENSG00000165660.
Subcellular location: Cytoplasm; Nucleus; Cytoplasm, cytoskeleton, spindle pole; Cytoplasm, cytoskeleton
Subcellular location (Human Protein Atlas): Cytosol; Basal body; Primary cilium transition zone
Pathways (Reactome):
Metabolism of proteins: Metalloprotease DUBs
Gene Ontology:
Molecular function: microtubule binding; polyubiquitin modification-dependent protein binding; protein binding
Biological process: attachment of spindle microtubules to kinetochore; chromosome segregation; mitotic cell cycle; mitotic spindle assembly; protein K63-linked deubiquitination; response to ischemia; response to vitamin B6
Cellular component: BRISC complex; centrosome; cytoplasm; cytosol; microtubule minus-end; midbody; nucleus; spindle pole centrosome; cytoskeleton; spindle pole
Genetic constraint (gnomAD): Loss-of-function variants: 12 observed, 30.35 expected, observed/expected ratio (o/e) 0.4, 90% interval 0.25 to 0.64. The upper end of that interval is the gene's LOEUF score, 0.64, which puts it in group 2 of 6, group 1 being the genes least tolerant of losing a copy. Missense variants: 351 observed, 410.03 expected, observed/expected ratio (o/e) 0.86, 90% interval 0.78 to 0.94. Synonymous variants: 121 observed, 149.21 expected, observed/expected ratio (o/e) 0.81, 90% interval 0.7 to 0.94.
Homologues: Orthologues: chimpanzee ABRAXAS2 (99% identical), macaque ABRAXAS2 (99% identical), dog ABRAXAS2 (95% identical), rabbit ABRAXAS2 (94% identical), pig ABRAXAS2 (94% identical), rat Abraxas2 (94% identical), mouse Abraxas2 (93% identical), zebrafish abraxas2 (61% identical), tropical clawed frog abraxas2 (61% identical). Paralogues in human: ABRAXAS1 (28% identical).
Diseases named in the same sentence as ABRAXAS2 in open-access papers:
ABRAXAS2 is named in the same sentence as 25 diseases in open-access papers, as found by Europe PMC text mining. Sharing a sentence is not in itself a finding about the gene and the disease.
ABRAXAS2 shares sentences with these, for which no sentence is quoted: tumor (5 papers); breast carcinoma (3); cancer (3); esophageal squamous cell carcinoma (2); osteosarcoma (2); thyroid cancer (2); atherosclerosis (1); cocaine dependence (1); colon cancer (1); esophageal carcinoma (1); Hepatitis (1); hepatocellular carcinoma (1); inflammatory bowel disease (1); inflammatory liver diseases (1); intraepithelial neoplasia (1); kidney tumors (1); liver cancer (1); lung carcinoma (1); neuroblastoma (1); non-small cell lung carcinoma (1); peritonitis (1); renal carcinoma (1); renal cell carcinoma (1); Sepsis (1); thyroid gland tumour (1).